FAP (fibroblast activation protein alpha)
Diseases named in the same sentence as FAP in open-access papers (continued):
Sharing a sentence is not in itself a finding about the gene and the disease.
tumor (continued). "We next performed data integration between publicly available single-cell transcriptomics data of CRC MSCs and our own datasets to validate tumor-specific FAP+ fibroblasts." (PMID 35365629, 2022). "We also performed [18F]FAPI-74 PET in PANC-1 xenograft mice and confirmed the high uptake in the tumour as well as the confirmation of FAP expression in the tumour stroma by immunohistochemistry." (PMID 34537893, 2022). "Elevated level of FAP expression was more likely to be correlated with a worse survival and a more advanced tumor stage." (PMID 35359436, 2022). "Due to the specific expression of FAP in tumor stromal fibrous tissues, FAP has received increasing attention as a specific marker of CAFs." (PMID 36531015, 2022). "All resected peritoneal metastases showed nests of tumour cells surrounded by FAP-expressing stroma." (PMID 35296803, 2022). "FAP5-DM1, a monoclonal antibody targeting FAP + CAFs, induces long-lasting suppression of tumor growth and complete regression in xenograft models of a series of cancers with no obvious toxicity." (PMID 35488263, 2022). "Briefly, 280 patients (81.4%) had low FAP expression, and 64 patients (18.6%) had high FAP expression in tumor cells." (PMID 35818720, 2022). "It was indeed confirmed that [177Lu]Lu-FAP-2286 had an extended tumor retention compared to [177Lu]Lu-FAPI-46 in a FAP-positive tumor bearing mouse model." (PMID 36182995, 2022). "For a more comprehensive examination, FAP immunohistochemistry was performed on whole FFPE tissue sections of 16 tumor types that included primary and metastatic samples of both low- and high-grade histology (n = 359)." (PMID 35608703, 2022). "After response to FAPα, the “uncaged” MB can recover its fluorescence and phototoxicity for tumor imaging and cytotoxic singlet oxygen (1O2) generation, eventually achieving accurate imaging-guided PDT." (PMID 35664057, 2022). "Next, we investigated in more detail which cell populations of the tumor-infiltrating leukocytes express FAP." (PMID 36230765, 2022). "Fibroblast activation protein (FAP) is highly expressed in a variety of epithelial cancers, and FAP inhibitor (FAPI) PET/CT has been used for various tumor imaging." (PMID 35712249, 2022). "In preclinical patient-derived xenograft models, hyperclustering dependent on the tumor cells’ apoptotic pathway and binding to FAP-positive stroma led to durable tumor reduction, which is currently being assessed in phase-I clinical research." (PMID 36389699, 2022). "In PDAC, known to be an immunologically “cold” tumor, the use of FAP-specific CAR T cells restrained tumor growth as well as reduced vasculature in the tumor through a mechanism that was immune-independent but stromal-dependent." (PMID 34200702, 2021). "Recent investigations indicated that 68Ga-labelled FAP inhibitor (FAPI) shows an equal or even improved tumour imaging with lower background uptake in the liver and the brain in comparison to 18F-FDG in various cancers." (PMID 34249748, 2021). "FAP inhibition enhanced the anti-tumor activity of immune checkpoint inhibitors, but it did not improve survival in a PDAC mouse model in one of the studies." (PMID 34203869, 2021). "For instance, in a mouse model for colon cancer inhibited tumor growth and metastatic dissemination, they targeted and killed FAP-positive cells via an oral DNA vaccine." (PMID 33806802, 2021). "In this array, KCNJ8 showed a higher expression in CAFs (FAP+) compared to tumor epithelial (EpCAM+) cells." (PMID 33802791, 2021). "In a mouse model, depletion of FAP-positive fibroblasts resulted in cytokine-induced hypoxic necrosis of tumor cells, highlighting the critical role of fibroblasts in tumor immune suppression." (PMID 34681633, 2021). "FAP is involved in a variety of tumor promoting activities such as matrix remodeling, angiogenesis, chemotherapy resistance and immunosuppression." (PMID 34417894, 2021).
tumor (continued). "αFAP-PE38 depleted FAP positive BCAFs, changed levels of chemokines, cytokines, and MMPs, and reduced tumor growth in the 4T1 TNBC model." (PMID 34944738, 2021). "Currently, the majority of in vitro researches on perivascular cells are performed on human brain vascular pericytes (HBVPs) and HBVPs are co‐cultured with cancer cells or transfected with FAPα to mimic tumour perivascular cells." (PMID 34035882, 2021). "The introduction of radiolabeled FAP-based inhibitors has led to a new class of radiopharmaceuticals used for visualizing FAP presented in the tumor stroma." (PMID 34681246, 2021). "In our study, the highest incidence of FAP+ cells were observed in tumors surrounded by a stroma, which prevents the migration of the immune cells into the tumor (T-cell exclusion pattern)." (PMID 34298868, 2021). "Due to its frequent overexpression in the tumor microenvironment and its plasma membrane localization, FAP is considered a promising molecular target for the imaging and treatment of malignant tumors." (PMID 33494271, 2021). "Following virus inoculation in cultivation media, viral infection and BiTE expression were detected in malignant tissue containing EpCAM-positive tumor cells and FAP-expressing CAFs via immunohistochemistry (IHC) and fluorescence microscopy." (PMID 33863363, 2021). "From the reports of previous studies and our study on [177Lu]Lu-DOTA.SA.FAPi, it is evident that the main challenge for the potential therapeutic application of the FAP tracers was to optimize its tumor retention time." (PMID 34959613, 2021). "We showed that targeting FAP on a second distinct cell line allowed to deliver co-stimulatory signals to T cells targeting a conventional TAA on other tumor cells." (PMID 34484225, 2021). "As stromal fibroblasts are highly present in the tumor microenvironment and contribute to progression and metastasis, FAP-expressing stromal cells were an attractive target for CAR-based therapy." (PMID 36284896, 2021). "Our results demonstrated that the proportion of fascin-positive staining in tumor cells correlates with that of FAP, α-SMA, and fascin-positive cells in CAFs (P < .05)." (PMID 34477172, 2021). "We observed variable FAP immunopositivity in individual cancer cells scattered in the tumour tissue or forming small clusters in 25.5% of tumours." (PMID 34282761, 2021). "In models of multidrug resistant murine colon and breast cancers, the use of a FAP DNA vaccine taken orally in a prophylactic setting led to a decrease in tumor growth." (PMID 34200702, 2021). "By chelation of various radiometals, these radiopharmaceuticals showed high affinity binding and rapid internalization into FAP-expressing tumor cells in radioligand assays." (PMID 34417894, 2021). "Because PDAC is characterized by its prominent and dense stroma that mainly consists of CAFs, FAP is a high potential target for high-contrast tumor-targeted imaging of PDAC." (PMID 34885196, 2021). "In PET studies, tumor uptake of [18F]F-Glc-FAPI in human FAP-transfected HT-1080 tumor-bearing mice was higher (4.6%ID/g) compared to [68Ga]Ga-FAPI-04 (2.1%ID/g)." (PMID 34681246, 2021). "Using this probe, we demonstrate both spatial localization and pseudo-quantitative characterization of FAP activity over wide fields of view in rodent brains harboring xenografts that display FAP expression comparable to patient-derived tumor cell lines." (PMID 34931988, 2021). "Fibroblast activation protein (FAP) is a serine protease which is upregulated in several tumor types, while its expression in healthy adult tissues is scarce." (PMID 34298822, 2021). "used FAP-targeting bispecific T-cell engager (FBiTE) inserted in the ICOVIR15K oncolytic adenovirus under the control of a major late promoter to direct tumor infiltrated lymphocytes against CAFs." (PMID 34305902, 2021).
tumor (continued). "The post-therapy whole-body scans, including SPECT/CT, showed high tumor accumulation and prolonged retention time of [177Lu]Lu-FAP-2286 in all patients at 72 h to 10 days post-injection." (PMID 34681246, 2021). "Normalization of the tumor microenvironment through the therapeutic targeting of FAP-expressing cells has been successfully addressed in several studies using animal models." (PMID 34209651, 2021). "We further verified the relationship between FAP expression and tumor-infiltrating immune cells by IHC staining of GC tissue microarrays (n = 31)." (PMID 35155199, 2021). "The same group used diphtheria toxin receptor-expressing transgenic mice to study the role of FAP in PDAC and found that eliminating FAP+ cells significantly reduces tumor growth, which is related to CD4+/CD8+ T-cell activity." (PMID 34490078, 2021). "With this approach, they targetedinfiltrated lymphocytes against FAP‐expressing CAFs, simultaneously targetingcancer cells and redirecting immune responses towards the tumour stroma fibroblast toimprove tumour permeability and virus spread." (PMID 33638871, 2021). "4% of TASCs isolated from PyMT:ChOVA tumours express syndecan‐2, 3.88% syndecan‐2+FAP− and 0.5% syndecan‐2+FAP+." (PMID 33152121, 2021). "FAP is a promising target for cancer molecular targeting therapy which was widely distributed in the tumor stroma." (PMID 33816303, 2021). "Inhibition of DPP4, DPP8, DPP9 and FAP by Val-boroPro has been shown to mediate regression in multiple tumour models, likely, at least in part, via the modulation of immune responses." (PMID 34771657, 2021). "We found that the majority of HLA-positive tumors have diffuse distribution of FAP+ fibroblasts in the stroma within the tumor mass, with only 7% of them demonstrating a peritumoral stromal capsule." (PMID 34298868, 2021). "A separate study found that FAP deletion also led to decreased tumor invasion and metastasis in preclinical PDAC models." (PMID 34948209, 2021). "The coupling of squaramide linker–target vector (FAP inhibitor) to dimers significantly increases tumor uptake, tumor retention, and low background." (PMID 34959613, 2021). "The tumor retention time of FAP inhibitor compounds has evolved since their first introduction; however, dose-escalation studies to achieve tumoricidal effects and optimize the therapeutic efficacy for different tumors require further research." (PMID 34858834, 2021). "For example, the conditional ablation of FAP+ cells using diphtheria toxin depletion in a PDAC model reduced tumor growth and re-established tissue homeostasis." (PMID 34359823, 2021). "As described in the previous sections, FAP expression appears to be related to the occurrence and development of malignant tumors, and FAP expression appears to be highly specific to tumor tissues." (PMID 34490078, 2021). "Genetic deletion of FAP in a KPC model led to decreased tumor growth, with improved immune surveillance and synergy with anti PD-1 and anti CTLA-4 therapies, an effect that resulted from a reduction in CAF-mediated CXCL12 secretion." (PMID 34948209, 2021). "Fibroblast activation protein (FAP, FAP-α), a type-II transmembrane serine protease acts on various hormones and extracellular matrix components which has an important role for tumor biology." (PMID 33864154, 2021). "For the SA vector, T cell-mediated lysis of FAP-positive cells, also in healthy donor-derived bone marrow samples, required presence of AdV-permissive tumor cells, indicating tumor cell-restricted virus replication and BiTE secretion and thus enhanced safety." (PMID 33863363, 2021). "Based on the high expression characteristics of FAP in tumor tissues, fluorescent probes and combined prodrug probes that respond to FAP enzyme activity have been designed to diagnose tumors." (PMID 34490078, 2021). "Immunohistochemistry analysis further confirmed the increased expression levels of α‐SMA, fibroblast activated protein (FAP) and collagen IV within tumours." (PMID 33713546, 2021).
tumor (continued). "Adding to this complexity, it was recently shown that in 4T1 tumours, FAPα+PDPN+ CAFs are capable of producing nitric oxide (NO), controlling the proliferation of effector T-cells, thus helping to create an immunosuppressive TME in TNBC." (PMID 34016130, 2021). "It has been reported that the degree of hypoxia correlates positively with tumour size and that hypoxia is a potent factor inducing the expression of FAP in CAFs." (PMID 34249748, 2021). "The quantity of FAP+ stromal cells positively correlated with tumour vascularisation (Kendal correlation coefficient 0.44, p < 0.001) and with the presence of microvascular proliferations (Kendal correlation coefficient 0.47, p < 0.001)." (PMID 34282761, 2021). "Targeting fibroblasts with high expression of fibroblast activation protein-α (FAP) in tumor-bearing mice have induced tumor necrosis mediated by IFN-γ and TNF-α, demonstrating that anti-tumor immunity has been reverted upon depletion of these cells." (PMID 34568077, 2021). "In this way, the toxic melittin is generated in tissues, in which FAP is present, leading to the death of both stromal cells inside the tumour and tumour cells and endothelial cells surrounding the stromal cells." (PMID 34067049, 2021). "Isolated CAFs expressed α-smooth muscle actin (α-SMA) and FAP at higher levels than 4T1 tumor cells." (PMID 33562504, 2021). "The increased expression of FAP in the tumor stroma and its absence from healthy adult tissues make this marker an especially attractive target for anti-cancer gene therapies." (PMID 34361120, 2021). "In contrast, 20% of FAP+ mesenchymal cell cultures in our study resembled original tumour tissues on the genomic level." (PMID 34282761, 2021). "FAP-specific inhibitors were developed and consecutively advanced into tumor-targeting radiopharmaceuticals leading to the recent introduction of [68 Ga]Ga-FAPI-04 PET/CT." (PMID 34226953, 2021). "Biodistribution studies in FAP positive tumor mice showed high specific uptake of [18F]AlF-NOTA-FAPI-04 in the tumor and FAP expressing tissues with little or no in vivo defluorination." (PMID 33816303, 2021). "A phase 2 trial of FAP inhibition using a humanized monoclonal antibody sibrotuzumab failed due to ongoing tumor progression in colorectal cancer patients (NCT02198274)." (PMID 33572223, 2021). "We found that a high expression level of PAI-1 in the tumor stroma was closely correlated with depth of tumor invasion (p < 0.001), high expression levels of αSMA (p < 0.001) and FAP (p < 0.001), and high numbers of infiltrating CD204+ macrophages (p = 0.002)." (PMID 33311557, 2021). "In several tumour types, FAP+ stromal cells contribute to immunosuppression, cancer cell growth, and it has been proposed that they also contribute to angiogenesis." (PMID 34282761, 2021). "Approximately 80% of fibroblasts are activated in tumor tissues, and FAP plays a crucial role in fibroblast activation." (PMID 33732680, 2021). "FAP proteins expression level was significantly upregulated in tumor tissues, which was consistent with previous results." (PMID 34802453, 2021). "A more sophisticated approach involved CAR T cells that specifically killed FAP+ CAFs, delaying tumor growth in mice." (PMID 33806802, 2021). "The design of these analyses did not, however, enable to address the possible prognostic role of FAP expression in individual cell types in the tumour microenvironment." (PMID 34282761, 2021). "The participation of FAP in a cell invasiveness, proliferation, migration and tumor vascularization has been described." (PMID 33669938, 2021). "On the other hand, the biodistribution of [177Lu]Lu-FAP-2286 in Sarc4809 xenografts injected at the same radioactivity dose as in the FAP-transfected HEK xenografted mice showed only 5.9%ID/g tumor uptake after 3 h post-injection." (PMID 34681246, 2021). "These nanoparticles break down in response to FAP activity, resulting in rapid and effective drug release at the tumor site." (PMID 34490078, 2021).
tumor (continued). "In this review, we summarized the recent progress in FAP expression and functional roles within tumor microenvironments." (PMID 34068501, 2021). "Since these cells are present in most cancerous tissues and FAP is rarely expressed in healthy tissues, anti-FAP tracers have a potential as pan-tumor agents." (PMID 34830898, 2021). "These properties make FAP a very interesting and universally applicable tumor target for a variety of tumor types." (PMID 34201111, 2021). "When adoptively transferred into mice, there was a reduction in highly expressing FAP stromal cells as well as a reduction in the tumor growth of subcutaneous tumors transplanted into mice." (PMID 34200702, 2021). "68Ga-FAPI-04 has low nanomolar affinity to FAP, is almost completely internalized, has a rapid blood clearance, and showed excellent image contrast in across many tumor entities." (PMID 34735669, 2021). "CAF overexpression of FAP promotes tumor development and metastasis by influencing extracellular matrix remodeling, intracellular signaling, angiogenesis, epithelial-to-mesenchymal transition, and immunosuppression." (PMID 34490078, 2021). "In CEA-positive tumor cells and a FAP-positive fibroblast mixture tumor model, combination therapy markedly suppressed tumor growth whereas T-BsAb monotherapy failed." (PMID 34832954, 2021). "Since rapid cell death was induced specifically and locally for CAFs, FAP-targeted NIR-PIT suppressed tumor progression and overcame chemoresistance in an esophageal tumor model without adverse effects." (PMID 34064074, 2021). "The developed FAP-selective ABPs can be used to facilitate the understanding of FAP’s enzymatic activity in the tumor microenvironment." (PMID 33996747, 2021). "Fibroblast activation protein (FAP) is a membrane-bound protease that is upregulated in a wide range of tumours and viewed as a marker of tumour-promoting stroma." (PMID 34282761, 2021). "FAP-positive CAFs attract Gr-1+/CD11b+ myeloid cells, and co-injection of FAP-positive CAFs and tumor cells into immunocompetent mice increases the frequency of infiltration of macrophages." (PMID 33572223, 2021). "In vivo, vaccine-induced depletion of FAP-positive cells resulted in reduced tumor growth and less metastatic dissemination." (PMID 33806802, 2021). "To investigate the relationship between FAP expression and clinical characteristics, we found that FAP was increasing with the development of tumor stage." (PMID 34035230, 2021). "In global CCR2 knockout mice, FAP-positive CAFs fail to promote tumor growth in a liver tumor xenograft model." (PMID 33572223, 2021). "Positive fascin staining in tumor cells correlated with all 3 markers, fascin, FAP, and α-SMA, staining CAFs (P < .05)." (PMID 34477172, 2021). "The findings above support that the SHH/GLI signaling pathway enables FAP to be involved in tumor growth and migration and the EMT process." (PMID 34068501, 2021). "Due to this reason, FAP is widely recognized as a crucial biomarker to identify potential CAF-positive tumor stroma." (PMID 34681246, 2021). "In conclusion, in the primary cohort of MPM patients including long‐term survivors, high FAP and SPARC expression in stromal cells and high PDGFRB expression in tumor cells were associated with shorter survival." (PMID 33955203, 2021). "The broad range of FAP expression in a variety of cancers has led to numerous studies regarding the pro-tumor and anti-tumor effects of FAP expression." (PMID 34490078, 2021). "We found that FAP was responsible for the tumor-promoting ability and immunosuppressive phenotype of CAFs." (PMID 33311557, 2021). "68Ga-FAPI-04 is a newly developed tumor imaging tracer which targets fibroblast activation protein (FAP)." (PMID 34181149, 2021). "Immunized mice produce antibodies to FAP, which can be detected in their serum, and this FAP-based heterogeneous whole-cell tumor vaccine treatment is a potential strategy for personalized immunotherapy in cancer patients." (PMID 34490078, 2021).